CSNK2A1 (casein kinase 2 alpha 1)
Description:
Catalytic subunit of a constitutively active serine/threonine-protein kinase complex that phosphorylates a large number of substrates containing acidic residues C-terminal to the phosphorylated serine or threonine. Regulates numerous cellular processes, such as cell cycle progression, apoptosis and transcription, as well as viral infection. May act as a regulatory node which integrates and coordinates numerous signals leading to an appropriate cellular response. Phosphorylates a number of DNA repair proteins in response to DNA damage, such as MDC1, MRE11, RAD9A, RAD51 and HTATSF1, promoting their recruitment to DNA damage sites. Can also negatively regulate apoptosis. Phosphorylates the caspases CASP9 and CASP2 and the apoptotic regulator NOL3. Phosphorylation protects CASP9 from cleavage and activation by CASP8, and inhibits the dimerization of CASP2 and activation of CASP8. Phosphorylates YY1, protecting YY1 from cleavage by CASP7 during apoptosis. Regulates transcription by direct phosphorylation of RNA polymerases I, II, III and IV. Also phosphorylates and regulates numerous transcription factors including NF-kappa-B, STAT1, CREB1, IRF1, IRF2, ATF1, ATF4, SRF, MAX, JUN, FOS, MYC and MYB. Phosphorylates Hsp90 and its co-chaperones FKBP4 and CDC37, which is essential for chaperone function. Mediates sequential phosphorylation of FNIP1, promoting its gradual interaction with Hsp90, leading to activate both kinase and non-kinase client proteins of Hsp90. Regulates Wnt signaling by phosphorylating CTNNB1 and the transcription factor LEF1. Acts as an ectokinase that phosphorylates several extracellular proteins. During viral infection, phosphorylates various proteins involved in the viral life cycles of EBV, HSV, HBV, HCV, HIV, CMV and HPV. Phosphorylates PML at 'Ser-565' and primes it for ubiquitin-mediated degradation. Plays an important role in the circadian clock function by phosphorylating BMAL1 at 'Ser-90' which is pivotal for its interaction with CLOCK and which controls CLOCK nuclear entry (By similarity). Phosphorylates CCAR2 at 'Thr-454' in gastric carcinoma tissue. Phosphorylates FMR1, promoting FMR1-dependent formation of a membraneless compartment. May phosphorylate histone H2A on 'Ser-1'.
Synonyms: CK2A1; Cka1; Cka2; CKII; OCNDS
Tractability: Small molecule: a drug acting on it is in phase 2 or 3 trials; a structure with a bound ligand is known; a high-quality ligand is known; it has a high-quality binding pocket; it belongs to a druggable protein family. Antibody: its Gene Ontology location is reachable by antibodies, with high confidence. PROTAC: it is named in the literature on targeted protein degradation; ubiquitination databases record sites on it; its protein half-life has been measured; a small molecule that binds it is known.
Target class: Enzyme; Other protein kinase group; Protein Kinase; Other protein kinase CK2 family; Kinase
Chemical probes: CHEMBL2062577, ELLAGIC ACID, GW869516X (high quality), PD085030, PD134330, SGC-CK2-1 (high quality), SGC-CK2-2 (high quality), SILMITASERTIB (high quality)
Gene: Protein-coding gene on chromosome 20 (472,498 to 543,835, reverse strand). Ensembl gene ENSG00000101266.
Subcellular location: Nucleus
Subcellular location (Human Protein Atlas): Nucleoplasm; Primary cilium
Pathways (Reactome):
Circadian clock: Phosphorylation and nuclear translocation of BMAL1 (ARNTL) and CLOCK; Phosphorylation and nuclear translocation of the CRY:PER:kinase complex
Gene expression (Transcription): RUNX1 interacts with co-factors whose precise effect on RUNX1 targets is not known
Signal Transduction: Regulation of PTEN stability and activity; WNT mediated activation of DVL
Autophagy: Receptor Mediated Mitophagy
Cell Cycle: Condensation of Prometaphase Chromosomes
Cell-Cell communication: Regulation of CDH1 posttranslational processing and trafficking to plasma membrane
Cellular responses to stimuli: KEAP1-NFE2L2 pathway
Developmental Biology: Signal transduction by L1
Disease: Maturation of hRSV A proteins
Immune System: SPOP-mediated proteasomal degradation of PD-L1(CD274)
Metabolism: Synthesis of PC
Metabolism of proteins: Cooperation of PDCL (PhLP1) and TRiC/CCT in G-protein beta folding
Gene Ontology:
Molecular function: identical protein binding; kinase activity; protein binding; protein serine kinase activity; protein serine/threonine kinase activity; Hsp90 protein binding; ATP binding; protein kinase activity
Biological process: DNA damage response; double-strand break repair; negative regulation of apoptotic signaling pathway; negative regulation of double-strand break repair via homologous recombination; negative regulation of proteasomal ubiquitin-dependent protein catabolic process; negative regulation of translation; peptidyl-serine phosphorylation; positive regulation of aggrephagy; positive regulation of cell growth; positive regulation of cell population proliferation; positive regulation of protein catabolic process; positive regulation of Wnt signaling pathway; protein stabilization; regulation of chromosome separation; symbiont-mediated disruption of host cell PML body; heterochromatin formation; positive regulation of DNA-templated transcription; protein folding; signal transduction; regulation of protein catabolic process
Cellular component: nucleoplasm; nucleus; PcG protein complex; PML body; protein kinase CK2 complex; Sin3-type complex; chromatin; cytosol; plasma membrane; PRC1 complex
Genetic constraint (gnomAD): Loss-of-function variants: 8 observed, 52.76 expected, observed/expected ratio (o/e) 0.15, 90% interval 0.088 to 0.27. The synonymous counts are far from expectation, so gnomAD's model fits this gene poorly and the ratio says little. Missense variants: 147 observed, 459.79 expected, observed/expected ratio (o/e) 0.32, 90% interval 0.28 to 0.37. Synonymous variants: 115 observed, 154.74 expected, observed/expected ratio (o/e) 0.74, 90% interval 0.64 to 0.87.
Gene-disease validity (ClinGen):
ClinGen rates the evidence that CSNK2A1 causes each of these diseases.
syndromic intellectual disability (autosomal dominant): Definitive. A intellectual disability that is part of a larger syndrome.
Homologues: Orthologues: chimpanzee CSNK2A1 (100% identical), dog CSNK2A1 (100% identical), macaque CSNK2A1 (100% identical), rabbit CSNK2A1 (100% identical), mouse Csnk2a1 (99% identical), rat Csnk2a1 (98% identical), tropical clawed frog csnk2a1 (90% identical), zebrafish csnk2a4 (81% identical), Drosophila melanogaster CkIIalpha (75% identical), Caenorhabditis elegans kin-3 (72% identical). Paralogues in human: CSNK2A3 (98% identical), CSNK2A2 (74% identical).
Diseases named in the same sentence as CSNK2A1 in open-access papers:
CSNK2A1 is named in the same sentence as 112 diseases in open-access papers, as found by Europe PMC text mining. Sharing a sentence is not in itself a finding about the gene and the disease. The quoted sentences say what the papers report.
breast carcinoma (18 papers, 2014 to 2024). "Furthermore, higher expression of CSNK2A1 is associated with shorter survival in patients with breast cancer, clear cell renal cell carcinoma, and gastric cancer." (PMID 34359939, 2021). "The association between CSNK2A1 with ER+ breast cancer was explained by SNP rs434410." (PMID 27942580, 2016). "Overexpression of CSNK2A1 is reported to play an important role in various cancers including gastric cancer and breast cancer." (PMID 39795915, 2024). "Previous studies have demonstrated that CSNK2A1 promotes tumorigenesis by enhancing several oncogenic signaling pathways in various malignancies, including breast cancer, lung cancer, kidney cancer, colorectal cancer, and prostate cancer." (PMID 38652547, 2024). "In a model of breast cancer BM, phase separation involved CSNK2A1 in the regulation of Wnt/β-catenin signaling." (PMID 37542040, 2023). "In the cytoplasm, SNHG3 facilitated the expression of Casein kinase II-A1 (CSNK2A1) by absorbing miR-485-5p and recruiting the HuR protein, participating in the malignant progression of breast cancer." (PMID 37348024, 2023). "It is known that CSNK2A1 promotes proliferation and invasiveness of breast cancer cells through mediating phosphorylation of SIRT6." (PMID 36050449, 2022). "Specifically, with regards to the subcellular localization of CSNK2A1, its high expression in the nucleoli of breast cancer cells predicted shorter survival of patients in univariate and multivariate analysis." (PMID 34359939, 2021). "In breast cancer cells, CSNK2A1 phosphorylates SIRT6 on Ser338, and this process stimulates cell proliferation through the regulation of β-catenin and NFκB." (PMID 34359939, 2021). "The most significant gene associations (P⩽0.01) were BAIAP2 and CALM2 for overall breast cancer; BAIAP2 and CSNK2A1 for ER+ breast cancer; and BRAF, BAD, and MAPK3 for ER− breast cancer." (PMID 27942580, 2016). "Inhibition of CSNK2A1 decreased the proliferative and invasive activity of breast cancer cells." (PMID 37007126, 2023). "In breast cancer cells, CSNK2A1 is involved in the EMT by regulating the Wnt/β-catenin pathway." (PMID 34359939, 2021). "In addition, the prognostic significance of CSNK2A1 in human cancer patients has been reported in various types of cancers, such as breast cancer, clear cell renal cell carcinoma, colon cancer, gastric cancer, and prostatic cancer." (PMID 34359939, 2021). "Notably, CSNK2A1 transcripts and proteins are reported to be upregulated in many kinds of cancers 4,22, such as multiple myeloma 23, breast cancer 11, and liver cancer." (PMID 31929734, 2020). "No CSNK2A1 SNPs have been previously reported associated with breast cancer." (PMID 27942580, 2016). "Our study has made groundbreaking progress in identifying key transcription factors, such as SP1, E2F1, and SIN3A, as well as kinases, including MAPK14, CSNK2A1, and CDC2, whose role in breast cancer progression is paramount." (PMID 38084295, 2023). "CSNK2A1 also plays an important role in cancer invasiveness by activating the EMT pathway in colorectal cancer and breast cancer." (PMID 34359939, 2021). "BAIAP2 was associated with overall and ER+ breast cancer; CALM2 with overall breast cancer; CSNK2A1 with ER+ breast cancer; and BRAF, BAD, and MAPK3 with ER− breast cancer." (PMID 27942580, 2016). "RNA expression levels of CDC2L1, CDC2L2, CCNL1, CCNL2, CSNK2A1, CSNK2A2, and CSNK2B genes in breast cancer subtypes were analyzed." (PMID 25837326, 2015).
colorectal cancer (10 papers, 2007 to 2024). A primary or metastatic malignant neoplasm that affects the colon or rectum. "Consistently, upregulation of CSNK2A1 expression has been observed in various cancer types, including the colorectal cancer, stomach cancer, head and neck cancer, kidney cancer, and prostate cancer, compared to noncancerous tissues." (PMID 37348024, 2023). "Furthermore, the prognostic relevance of CSNK2A1 has been reported in multiple cancer types, including colorectal cancer, gastric cancer, clear cell renal cell carcinoma and prostatic cancer." (PMID 37348024, 2023).
prostate carcinoma (10 papers, 2016 to 2024). A carcinoma that arises from epithelial cells of the prostate gland. "In prostate cancer cells, CSNK2A1 transcript levels were unchanged, yet its protein levels were increased." (PMID 34773100, 2022). "Another aspect of FAN analysis relevant to its utility and implications for the role resveratrol plays in prostate cancer relates to the three primary targets of resveratrol: CSNK2A1, NQO2 and PTGS2." (PMID 27232943, 2016). "Additionally, a significant positive correlation was observed between CSNK2A1 and AR mRNA levels in prostate cancer." (PMID 36860677, 2023). "An excellent example of this was shown in a prostate cancer mouse xenograft model, where CSNK2A1 siRNA was delivered via a nanoparticle delivery system in PC3-LN4 engrafted mice, leading to a >50% reduction in tumour volume at 10 days after the start of treatment (p = 0.005)." (PMID 34773100, 2022).
Okur-Chung neurodevelopmental syndrome (9 papers, 2021 to 2025). "In 2016, identified by WES, mutations in CSNK2A1 were confirmed to be associated with the Okur-Chung neurodevelopmental syndrome." (PMID 41216289, 2025). "Okur-Chung Neurodevelopmental Syndrome (OCNDS) is an ultra-rare genetic disorder caused by de novo mutations in the CSNK2A1 gene, which encodes the catalytic subunit of protein kinase CK2α." (PMID 40677894, 2025). "This child presented with the typical clinical presentation of Okur-Chung neurodevelopmental syndrome due to a CSNK2A1 missense variant." (PMID 38096238, 2023). "CSNK2A1 is associated with Okur-Chung Neurodevelopmental Syndrome (OCNS, OMIM: 617062)." (PMID 41216289, 2025). "The CSNK2A1 gene is linked to Okur-Chung neurodevelopmental syndrome in OMIM." (PMID 40290421, 2025). "Examples of these include CSNK2A1 that was reported to be causative for Okur-Chung neurodevelopmental syndrome (OCNDS; OMIM #617062) in 2016 and ADPRHL2 that was associated with stress-induced childhood-onset neurodegeneration with variable ataxia and seizures (CONDSIAS; OMIM #618170) in 2018." (PMID 35710456, 2022). "Okur-Chung Neurodevelopmental Syndrome (OCNDS) is caused by heterozygous mutations to the CSNK2A1 gene, which encodes the alpha subunit of protein kinase CK2." (PMID 35517865, 2022). "Specific de novo mutations in the CSNK2A1 gene, which encodes CK2α, the catalytic subunit of protein kinase CK2, are considered as causative for the Okur-Chung neurodevelopmental syndrome (OCNDS)." (PMID 35445078, 2022).
gastric cancer (8 papers, 2021 to 2025). A primary or metastatic malignant neoplasm involving the stomach. "CSNK2, or casein kinase 2 (CK2), is involved in various cellular processes and has been implicated in tumor development, with CSNK2A1 overexpression shown to promote gastric cancer progression." (PMID 39408230, 2024). "CSNK2A1 was found to be significantly over-expressed in gastric cancer cells compared to normal gastric epithelium." (PMID 40453647, 2025). "In cases of gastric carcinomas, the immunohistochemical detection of CSNK2A1 expression has been found as a self-regulating prognostic factor associated with recurrence-free survival (RFS) and reduced overall survival in cancer patients." (PMID 37348024, 2023). "In gastric cancer cells, CSNK2A1 is involved in cancer progression by stimulating proliferation and invasiveness through the phosphorylation of DBC1/CCAR2 and the PI3K-Akt-mTOR pathway." (PMID 34359939, 2021). "In breast and gastric carcinomas, immunohistochemical expression of CSNK2A1 was an independent indicator of shorter OS and RFS in cancer patients." (PMID 34359939, 2021). "Similarly, CSNK2A1 has been reported as a protein with a positive role in gastric cancer and as a possible therapeutic target." (PMID 37047552, 2023). "For instance, CSNK2A1 promotes gastric cancer invasiveness via the PI3K-Akt-mTOR signal pathway; CSNK2A1 is a mediator of MEK/ERK inhibitor resistance in KRAS (G12C) mutant LC cells; CSNK2A1 is a promising new prognostic marker for renal cell carcinoma." (PMID 35266446, 2022). "Furthermore, it was demonstrated that CSNK2A1 regulates epithelial-to-mesenchymal transition (EMT) and enhances the invasiveness of gastric cancer cells through the PI3K–Akt–mTOR signaling pathway." (PMID 40453647, 2025). "Some kinases (e.g. PRKACA, CSNK2A1 and MAPK1) were found specifically dysregulated across multiple tumour types, but more than half were dysregulated in just one tissue (68%) such as MYLK kinase in stomach cancer and MTOR in kidney cancer." (PMID 36688815, 2023).
lung carcinoma (7 papers, 2010 to 2025). "Thus our study provides the first evidence that the CSNK2A1P 398T allele, which is similar to the CSNK2A1 gene, is amplified in human lung cancer tissues." (PMID 20625391, 2010). "While the role of CSNK2A1 in lung cancer has been established, its specific function in LUSC has yet to be fully investigated." (PMID 40028162, 2025). "The HIF, TGM2, CSNK1A1, CSNK2A1, CTNNA1, NAMPT)/Visfatin, TNFRSF1A, ETS1 and SRC-1 were down-regulated and proposed as the biomarkers for lung cancer." (PMID 23122428, 2012). "Research has shown that knocking down CSNK2A1 in KRAS (G12C) mutant lung cancer cells reduced cell proliferation, inhibited Wnt/β-catenin signaling, and enhanced the anti-proliferative effects of MEK inhibitors on KRAS (G12C) mutant lung cancer cells." (PMID 38155968, 2023). "Overexpression of the CSNK2A1 gene was also noted in above cancer cell lines, suggesting that in addition to the CSNK2A1 gene, the CSNK2A1P gene also plays important roles in the pathogenesis of lung cancer." (PMID 20625391, 2010). "Thus, the overall results indicated that OGR1 upregulates the expression of CSNK2A3 and NEP, but not CSNK2A1 in lung cancer cells." (PMID 35123428, 2022).
acute myeloid leukemia (4 papers, 2013 to 2024). Acute myeloid leukemia (AML) is a group of neoplasms arising from precursor cells committed to the myeloid cell-line differentiation. "CSNK2A1, a catalytic subunit of CK2, has been identified as a potential therapeutic target in acute myeloid leukemia." (PMID 38652547, 2024).
cervical cancer (4 papers, 2019 to 2022). A primary or metastatic malignant neoplasm involving the cervix. "Our results reveal that CSNK2A1‐dependent HMGA2 phosphorylation may partially underlie cisplatin‐resistance in cervical cancer, suggesting that HMGA2 phosphorylation may have potential as a predicative biomarker and therapeutic target to improve chemotherapeutic efficacy." (PMID 34115920, 2021). "The novelty of the present study is that we first demonstrated the role of the interaction of HMGA2 and CSNK2A1 in cisplatin resistance for cervical cancer." (PMID 34115920, 2021). "Furthermore, the present study confirmed the role of the interaction of HMGA2 and CSNK2A1 in cisplatin resistance for cervical cancer." (PMID 34115920, 2021). "However, the role of HMGA2 and CSNK2A1 in cervical cancer needs to be deciphered." (PMID 34115920, 2021). "For the first time, the interaction of CSNK2A1 and HMGA2 was confirmed in cervical cancer." (PMID 34115920, 2021).
epilepsy (4 papers, 2016 to 2025). A brain disorder characterized by episodes of abnormally increased neuronal discharge resulting in transient episodes of sensory or motor neurological dysfunction, or psychic dysfunction. "In one case, we found a de novo missense mutation in CSNK2A1, a gene not included in the epilepsy panel at the time." (PMID 40290421, 2025). "Several genes which have been linked to cell death in cancer, epilepsy, or psychological disorders but not yet associated with brain injury, including CSNK2A1, ELAVL1, MITF, and SMARCA4, were also identified which may provide additional therapeutic targets for prevention of cell death following TBI." (PMID 26912237, 2016).